AMOTL2 (angiomotin like 2)
Diseases named in the same sentence as AMOTL2 in open-access papers (continued):
Sharing a sentence is not in itself a finding about the gene and the disease.
tumor (continued). "In tumor affected areas of the intestinal epithelium, Lieberkühn Crypts exhibited a stronger grade of AmotL2 specific staining; however, the higher grade of expression in the crypts facing the muscularis mucosae observed in healthy colon was no longer visible." (PMID 28441737, 2017). "Additionally, we detected whether exosomal miR-149-5p regulated the growth and apoptosis of tumor cells by inhibiting AMOTL2." (PMID 33658392, 2021). "The expression of AmotL2 in ENS cells was evidenced by co-immunostaining with MAP2 and GFAP markers in non-tumor colon sections from untreated and OxPt-treated patients." (PMID 39335466, 2024). "The colocalization of CD34 (a telocyte marker) with AmotL2, FKBP51, and IQGAP1 in tumor vessels was indicative of a role for these three scaffold proteins in tumor angiogenesis and vascular invasion." (PMID 37415743, 2023). "Using immunofluorescence, we found that YAP1 downstream effectors identified in mRNA analysis, ANKRD1, AMOTL2 and AXL were increased in LATS1/2 cKO tumours." (PMID 32404936, 2020). "The co-localization of CD34 and AmotL2, FKBP51 and IQGAP1 in several vessels is indicative of a role for these three scaffoldings in tumor angiogenesis and/or in vascular invasion." (PMID 28441737, 2017). "Positive immunostaining for scaffold AmotL2, FKBP51 and IQGAP1 proteins was found in most cells in healthy colon, tumor, healthy liver and metastasized liver." (PMID 28441737, 2017). "As described in previous studies, AMOT family proteins including AMOTL2 exert a negative effect on YAP nuclear translocation, which is associated with tumor metastasis." (PMID 38956029, 2024). "Additionally, previous findings demonstrated the role of AMOTl2, one of AMOT family, as a tumor suppressor, where it decreased YAP tight junction localization, reduced the accumulation of nuclear YAP, and attenuated YAP phosphorylation." (PMID 34202571, 2021). "In our LATS1/2 cKO mouse model, although some of the tumour markers were highly present in the centre of the tumour mass, e.g., ANKRD1, Vimentin, CK18, nestin and Ki67, some were localised towards the edges of the tumour, e.g., HOPX, AMOTL2, AXL and microglial marker C3." (PMID 32404936, 2020). "Importantly, the increased tumorigenicity of MAGI1 deficient cells is rescued in the absence of AMOTL2 or after inhibition of p38, demonstrating that MAGI1 acts as a tumor-suppressor in luminal BCa by inhibiting an AMOTL2/p38 stress pathway." (PMID 33707576, 2021). "In addition, UCA1 could promote tumor growth and angiogenesis through the UCA1/miR-96-5p/AMOTL2, ERK1, ERK2 axis." (PMID 34760707, 2021). "The display in differential localization and quantitative expression of AmotL2, FKBP51, and IQGAP1 could be used as biomarkers for more accurate tumor staging and as potential targets for anti-cancer therapeutics by blocking or slowing down their interconnecting functions." (PMID 28441737, 2017).
cancer (14 papers, 2015 to 2025). A tumor composed of atypical neoplastic, often pleomorphic cells that invade other tissues. "Taken together, the functional roles of AMOT-p80, AMOT-p130, AMOTL1, and AMOTL2 in different cancer types are controversial and they highly depend on cell context." (PMID 29650031, 2018). "AMOTL2 was significantly increased in cancer compared to control by 1.2-fold, p = 0.006 (RT-PCR) vs. 1.7-fold, p = 0.0001 (Affymetrix microarray)." (PMID 25705890, 2015). "The immunophilin FKBP51, the angiomotin AmotL2, and the scaffoldin IQGAP1 are overexpressed in many types of cancer, with the highest increase in leucocytes from patients undergoing oxaliplatin chemotherapy." (PMID 35563891, 2022). "USP9X was first found to regulate YAP via direct or indirect mechanisms as a DUB of AMOTL2, LATS, or YAP in different cancers." (PMID 34055773, 2021). "Consistent with the observed IAG933 activity in a subset of Hippo-unaltered cell lines, additional profiling on 263 cancer cell lines revealed higher sensitivity in cells that display high basal TEAD activity, as determined by a four-gene (CCN1, CCN2, ANKRD1 and AMOTL2) transcriptional signature." (PMID 38565920, 2024). "AmotL2 modulates signaling pathways such as the Hsp70-Bag3 pathway, in which it scaffolds the LATS1 and YAP proteins of the Hippo pathway; it has also been shown to be involved in the epithelial to mesenchymal transition of a number of cancers." (PMID 35563891, 2022). "The metabolic rewiring of cancer cells modulates the activity of the energy stress sensor AMP‐activated kinase (AMPK), which in turn controls YAP/TAZ signaling directly (by direct phosphorylation of YAP) or indirectly (by activating LATS1/2 or AMOTL2)." (PMID 31633874, 2019).
colon (1 paper, 2024). "The human AMOTL2 gene encodes two protein isoforms, p100 and p60, the latter shown to induce loss of cell polarity and broad disruption of tissue architecture in human breast and colon cancers." (PMID 40295691, 2024).
inflammation (1 paper, 2023). Aberrant reaction of the microcirculation characterized by movement of fluid and leukocytes from the blood into extravascular tissues. "We showed that AmotL2-deficient cells acquire a pro-inflammatory phenotype with ensuing formation of areas of vascular inflammation characterized by the presence of Cd45+ monocytes." (PMID 39195920, 2023).
AMOTL2 also shares sentences with these, for which no sentence is quoted: meningioma (2 papers); glioma (1); Hernia (1); mantle cell lymphoma (1); nasopharyngeal carcinoma (1); neurological disorders (1); non-alcoholic steatohepatitis (1).